MST1 (macrophage stimulating 1)
Diseases named in the same sentence as MST1 in open-access papers (continued):
Sharing a sentence is not in itself a finding about the gene and the disease.
prion disease (3 papers, 2014 to 2022). A transmissible disease that is caused by a protein that is able to induce abnormal folding of normal cellular proteins, leading to characteristic spongiform brain changes, which are associated with neuronal loss without an inflammatory response. "The upstream activator of Mst1, c-Abl tyrosine kinase, led to mitochondrial abnormality, excessive ROS production and neuronal apoptosis in prion diseases." (PMID 35656021, 2022). "MST1 signaling was activated at 130 dpi, which had not been described in prion disease." (PMID 25183307, 2014). "However, caspase-3 activation is not required for MST1 activation or neuronal death in prion disease." (PMID 25183307, 2014).
subarachnoid hemorrhage (3 papers, 2017 to 2023). A serious neurological disorder characterized by intracranial hemorrhage into the subarachnoid space. "Furthermore, after subarachnoid hemorrhage, MST1 is activated and promotes neuronal apoptosis, which can be significantly inhibited by PCMT1." (PMID 37596654, 2023). "However, during subarachnoid hemorrhage, the involvement of MST1 in the pathophysiology of early brain injury remains unknown." (PMID 30018671, 2018).
adenoma (2 papers, 2013 to 2020). A neoplasm arising from the epithelium. "Mice with conditional double knockout of Mst1 and Mst2 in the intestinal epithelium were reported to develop adenomas in the colon by 13 weeks of age via activated Wnt and Notch signaling followed by YAP protein up-regulation." (PMID 33271948, 2020). "IEC-specific Mst1/Mst2 double knockout mice exhibit a short life span (13 weeks in median) with severe wasting signs and disorganized crypt–villus structure due to the hyperplasia of ISCs and undifferentiated cells are found in their intestinal tract, leading to adenoma formation." (PMID 33271948, 2020).
adenomyosis (2 papers, 2023 to 2025). The growth of endometrial tissue inside the muscular wall of the uterine corpus. "The western blot results showed that the expression of Mst1, p-Lats1, and p-YAP was increased, and the expression of YAP, Tead, and Cyr61 was decreased in the verteporfin group compared with the adenomyosis group." (PMID 36940085, 2023).
breast tumors (2 papers, 2020 to 2022). "In the METABRIC dataset, MST1 expression was highest in normal‐like breast tumors and lowest in claudin‐low breast tumors." (PMID 32484599, 2020).
chronic kidney disease (2 papers, 2023 to 2025). Impairment of the renal function secondary to chronic kidney damage persisting for three or more months. "It is showed that MST1/2 inhibits YAP activity of the renal tubules to inhibit the chronic kidney disease (CKD)." (PMID 37909712, 2023). "Conversely, glucose induced MST1 inactivation in renal tubular cells, results in YAP activation, its translocation into the nucleus, and EMT of renal tubular epithelial cells, resulting in renal fibrosis and chronic renal failure." (PMID 40468401, 2025).
ciliopathy (2 papers, 2021 to 2025). A genetic disorder of the cellular cilia or the cilia anchoring structures, the basal bodies, or of ciliary function. "Further, the Hippo kinases MST1/2-SAV1 promote ciliogenesis in 293T cells and depletion of Mst1/2-Sav1 resulted in ciliopathy phenotypes in zebrafish." (PMID 34422841, 2021).
eczema (2 papers, 2016 to 2017). "Highly elevated serum IgE levels, atopic manifestations such as severe eczema and allergies, and failure to thrive distinguish DOCK8 deficiency and WAS from MST1 deficiency." (PMID 26801501, 2016).
intrahepatic cholangiocarcinoma (2 papers, 2019 to 2025). A carcinoma that arises from the intrahepatic bile duct epithelium in any site of the intrahepatic biliary tree. "In the same line, hepatic inactivation of the MST1/2-adaptor protein SAV1/WW45 resulted in YAP-associated cell proliferation and mutant mice ultimately developed tumors with characteristics of HCC and intrahepatic cholangiocarcinomas (ICC)." (PMID 30931304, 2019).
ischemia (2 papers, 2023 to 2024). A hypoperfusion of the BLOOD through an organ or tissue caused by a PATHOLOGIC CONSTRICTION or obstruction of its BLOOD VESSELS, or an absence of BLOOD CIRCULATION. "We here demonstrate that C/EBP-β is activated through phosphorylation in the leucine zipper domain by Mst1 through a FoxO1-dependent mechanism, thereby protecting the heart against ischemia." (PMID 39060225, 2024). "Conversely, suppression of endogenous Mst1 activity in Tg-DN-Mst1 hearts significantly enlarged the area of MI during ischemia." (PMID 39060225, 2024). "Collectively, these results suggest that the Mst1–FoxO1–C/EBP-β pathway plays a protective role during ischemia in the heart." (PMID 39060225, 2024).
leukemia (2 papers, 2018 to 2020). A malignant (clonal) hematologic disorder, involving hematopoietic stem cells and characterized by the presence of primitive or atypical myeloid or lymphoid cells in the bone marrow and the blood. "Instead, we here define the RASSF2-proximal proteome in leukemia cells and demonstrate the critical importance of its endogenous interaction with Hippo kinases, MST1 and MST2, through the C-terminal SARAH domain." (PMID 32029705, 2020). "A proximity-based biotin labeling approach demonstrates that RASSF2 forms a discrete complex with MST1 and MST2 that is independent of the canonical Hippo pathway in leukemia cells." (PMID 32029705, 2020).
mastitis (2 papers, 2020). Inflammation of breast tissue during lactation or postpartum due to an obstructed duct or infection. "The NRG1, MST1, and NAT9 genes are closely related with the progression of S. aureus subclinical mastitis and serve as epigenetic markers for improving mastitis resistance in dairy cows." (PMID 32000686, 2020). "Genome-wide DNA methylation analysis of peripheral blood lymphocytes identified 1,078 differentially methylated genes between cows with S. aureus-mastitis and healthy cows, as well as the potential of NRG1, MST1, and NAT9 genes to serve as biomarkers of S. aureus mastitis progression." (PMID 33193625, 2020).
multiple myeloma (2 papers, 2016 to 2024). "Re-expression of YAP in multiple myeloma cells with YAP deletion or knockdown of MST1 in multiple myeloma cells with wild-type YAP, promoted apoptosis and growth arrest." (PMID 27042197, 2016).
myeloid leukemia (2 papers, 2020 to 2022). A clonal proliferation of myeloid cells and their precursors in the bone marrow, peripheral blood, and spleen. "With the increase in miR-887-5p expression through being transfected with mimics-miR-887-5p in THP-1 cells (human myeloid leukemia mononuclear cells), the expression of MST1 decreased and that of p38-MAPK increased." (PMID 36263059, 2022). "This revealed that the ability of MST1 to interact with RASSF2 through the SARAH domain, rather than its kinase activity towards canonical effectors, contributes to its function in myeloid leukemia cells." (PMID 32029705, 2020).
Myocardial fibrosis (2 papers, 2022 to 2024). "MST1 has also been reported to be associated with fibrosis and activated MST1 induces myocardial fibrosis after MI337." (PMID 35273164, 2022).
pneumonia (2 papers, 2017 to 2022). An acute, acute and chronic, or chronic inflammation focally or diffusely affecting the lung parenchyma, caused by an infection in one or both of the lungs (by bacteria, viruses, fungi, or mycoplasma.). "The hippo signaling pathway is mainly composed of MST1/2, LATS1/2, SAV1, MOB1, YAP, or TAZ, and TEAD and is involved in ALI, PAH, pneumonia, IPF, and asthma." (PMID 35443749, 2022).
psoriasis (2 papers, 2024 to 2025). An autoimmune condition characterized by red, well-delineated plaques with silvery scales that are usually on the extensor surfaces and scalp. "For instance, MST1, the upstream kinase of the Hippo pathway, was dramatically up-regulated in psoriasis patients’ skin lesions and T cells." (PMID 40108109, 2025). "Meanwhile, MST1 promotes the proliferation and activation of T cells, suggesting its role in psoriasis pathogenesis." (PMID 40108109, 2025). "For instance, Mst1 has been shown to promote NF-κB activation in brain tissues, cardiomyocytes, and skin lesions of psoriasis." (PMID 39253972, 2024).
T-cell immunodeficiency (2 papers, 2013 to 2019). A broad classification of disorders that affect the cell-mediated aspect of the immune response. "Previous reports have reported a systemic T cell lymphopenia due to defects in homing and survival in Mst1-KO mice, and Mst1-mutated patients with impaired T cell survival that resulted in primary T cell immunodeficiency." (PMID 31572367, 2019).
/T-cell lymphoma (1 paper, 2023). "Furthermore, the overexpression of MST1 or the knockdown of YAP inhibited cell proliferation, promoted cell-cycle arrest, and apoptosis in natural killer/T-cell lymphoma." (PMID 37910143, 2023).
actinopathies (1 paper, 2021). "In conclusion, a number of actinopathies are associated with alterations in the homing of lymphocytes and DCs to LNs (WASP, DOCK2, STK4/MST1) and/or in the egress of antigen-experienced lymphocytes from LNs (DOCK2, MSN, STK4/MST1)." (PMID 34867982, 2021).
acute lung injury (1 paper, 2024). A condition of lung damage that is characterized by bilateral pulmonary infiltrates (pulmonary edema) rich in neutrophils, and in the absence of clinical heart failure. "This study investigated the role of Mst1 in lung endothelial activation and acute lung injury (ALI)." (PMID 39253972, 2024).
aneurysm (1 paper, 2023). Bulging or ballooning in an area of an artery secondary to arterial wall weakening. "Paradoxically, MST1 promotes the inflammatory response and the mitochondrial dysfunction directly or by activating NF-κB signaling pathway in the process of aneurysm formation, finally to aggravate the inflammatory damage." (PMID 37909712, 2023). "Paradoxically, MST1 activates NF-κB signaling pathway to aggravate the inflammatory injury in the process of aneurysm formation." (PMID 37909712, 2023).
Atrophy (1 paper, 2013). Any weakening or degeneration, especially through lack of use. "By elucidating the MST1-FOXO3a signaling mechanism in neurogenic muscle atrophy, we provide a potential therapeutic target for the clinical treatment of muscle atrophy." (PMID 23374633, 2013). "Interestingly, MST2 protein level was not altered in this model of muscle atrophy, indicating MST1 and MST2 kinases play differential roles in mediating the occurrence of muscle atrophy." (PMID 23374633, 2013).
B cell lymphopenia (1 paper, 2018). "Conditional Mst1/2-deficient mice exhibited severe B cell lymphopenia, and an increase in the myeloid cell population and mild erythropenia in BM, spleen, and PB." (PMID 29343826, 2018).
bacterial pneumonia (1 paper, 2024). Acute infection of the lung parenchyma caused by bacteria (e.g., Streptococcus pneumoniae, Haemophilus influenzae, Chlamydia pneumoniae, Mycoplasma pneumoniae, and Legionella pneumophila). "Future studies will be needed to optimize the therapeutic regimen and test the efficacy of Mst1 inhibitors in other lung injury models such as a bacterial pneumonia model." (PMID 39253972, 2024).
Bovine mastitis (1 paper, 2016). INFLAMMATION of the UDDER in cows. "Further functional analysis revealed that three genes, NRG1, MST1 and NAT9, were strongly correlated with the progression of S. aureus subclinical mastitis and could be used as powerful biomarkers for the improvement of bovine mastitis resistance." (PMID 27411928, 2016).
brain inflammation (1 paper, 2023). "The IL-23 aptamer has been shown to have a neuroinflammatory suppressive effect by binding to macrophage stimulating 1 (MST1) kinase and blocking IL-23 in a mouse model of parathion-induced brain inflammation." (PMID 37511539, 2023).
brain tumor (1 paper, 2022). "The interaction of the STRIPAK complex with MAP4K4 confirms previous findings describing a direct interaction of STRIPAK with MST1/2, MST3/4, and MAP4Ks19,25,33,34 in a brain tumor, where MAP4K4 and STRN3/4 are highly expressed." (PMID 35941177, 2022).
candidiasis (1 paper, 2012). Infection with the organism Candida. "Furthermore, recurrent pulmonary infections, susceptibility to candidiasis and non regressing cutaneous warts caused by cutaneous alpha- and beta-HPVs have been reported in MST1-deficient patients." (PMID 22952854, 2012). "Here, based on whole-exome sequencing (WES), which has successfully been used to identify novel immune deficiencies, we describe the discovery of MST1 deficiency and a profound T-cell deficiency in a patient displaying EV-HPV infections as well as candidiasis and pulmonary infections." (PMID 22952854, 2012).
cervical disease (1 paper, 2020). "We discovered that expression of the master Hippo kinase, STK4 (also termed MST1), is reduced in HPV positive cervical cell lines and cervical disease samples." (PMID 32555725, 2020).
CHARGE syndrome (1 paper, 2023). CHARGE syndrome is a multiple congenital anomaly syndrome characterized by the variable combination of multiple anomalies, mainly Coloboma; Choanal atresia/stenosis; Cranial nerve dysfunction; Characteristic ear anomalies (known as the major 4 C's). "Murmur or cyanosis suggestive of congenital heart defects (particularly conotruncal anomalies) is associated with DGS, severe congenital neutropenia (SCN) type 4, CHARGE syndrome, Kabuki Syndrome, and MST1/STK4 deficiency." (PMID 37102642, 2023).
chronic cholecystitis (1 paper, 2020). "In an extended cohort of advanced GBC cases, we showed that expression of YAP1 and MST1 were reduced in GBC compared with chronic cholecystitis." (PMID 32218280, 2020). "Additionally, advanced GBC cases showed reduced expression of MST1 compared to chronic cholecystitis." (PMID 32218280, 2020). "Here, we determined the expression levels of the main components of the Hippo-YAP1 signaling pathway YAP1, TAZ and MST1 in GBC and chronic cholecystitis patients." (PMID 32218280, 2020).
colonic adenomas (1 paper, 2013). "Mst1/2 intestinal DKO mice (Mst1−/−Mst2fl/fl-villin-Cre) with ablation of both Mst1 and Mst2 in intestinal compartment are born normal at birth, however they develop colonic adenomas within 3 months old and can only survive for about 13 weeks (median age) accompanied by severe wasting." (PMID 23985272, 2013).
combined immunodeficiency (1 paper, 2016). A broad classification of inherited disorders presenting at birth that affect both the cell-mediated and humoral aspects of the immune response. "Recently, two studies have identified MST1 deficiency as the cause of combined immunodeficiency (CID) in three different families with homozygous nonsense mutations in the STK4 gene." (PMID 26801501, 2016).
COVID-19 (1 paper, 2025). A disease caused by infection with severe acute respiratory syndrome coronavirus 2. "Macrophage-stimulating 1 (MST1), a novel regulator of cell survival that is closely associated with tyrosine kinase receptor signaling, was significantly upregulated in both PLWH with COVID-19 and PLWH." (PMID 40568587, 2025).
cyst (1 paper, 2025). A sac-like closed membranous structure that may be empty or contain fluid or amorphous material. "We observed a significant enhancement in the levels of p‐MST1/2, p‐LATS and p‐YAP within renal cyst cells in NPH1 patients, which may indeed limit cyst growth and contribute to maintenance of the kidney size." (PMID 39995111, 2025).
depression (1 paper, 2025). "MST1 activation is also seen in the hippocampus but not pre-frontal cortices of a mouse model of depression." (PMID 41013661, 2025).
diffuse large B-cell lymphoma (1 paper, 2021). "In diffuse large B-cell lymphoma, IGF1R blockade using AG1024 or PPP or short hairpin RNA decreased the expression of the oncogenic YAP protein and enhanced MST1 expression, suggesting that the IGF1R might contribute in regulating the Hippo pathway." (PMID 34440844, 2021).
epilepsy (1 paper, 2025). A brain disorder characterized by episodes of abnormally increased neuronal discharge resulting in transient episodes of sensory or motor neurological dysfunction, or psychic dysfunction. "Since we identified that Hippo pathway kinase MST1/2 inhibitor XMU-MP-1 recovers GS in hyperammonemic condition, we prepared two rodent model of epilepsy and examined if XMU-MP-1 has an anti-epileptic effect by targeting astrocytic YAP and GS." (PMID 41390571, 2025).
Granuloma (1 paper, 2024). A compact, organized collection of mature mononuclear phagocytes, which may be but is not necessarily accompanied by accessory features such as necrosis. "Macrophages-specific Mst1 knockout mice exhibit worsened liver pathology with larger granulomas and increased fibrosis." (PMID 39700261, 2024). "Mice with macrophages-specific Mst1 knockout (termed Mst1△M/△M) mice developed exacerbated liver pathology, characterized by larger egg-induced granulomas, and increased fibrosis post infection." (PMID 39700261, 2024).
head and neck cancer (1 paper, 2025). A primary or metastatic malignant neoplasm affecting the head and neck. "In head and neck cancer, reduced MST1/2 activity is closely associated with sustained activation of YAP/TAZ, which in turn drives cell proliferation and invasion." (PMID 40486910, 2025).
Huntington disease (1 paper, 2020). Huntington disease (HD) is a rare neurodegenerative disorder of the central nervous system characterized by unwanted choreatic movements, behavioral and psychiatric disturbances and dementia. "Importantly, phosphorylated MST1—the active form of MST1—was reported to be significantly increased in the post-mortem cortex of patients with Huntington's disease (HD)." (PMID 32140159, 2020).
Hydrocephalus (1 paper, 2016). Hydrocephalus is an active distension of the ventricular system of the brain resulting from inadequate passage of CSF from its point of production within the cerebral ventricles to its point of absorption into the systemic circulation. "Although homologues of Lgl1 and aPKC in Drosophila regulate Hippo (hpo) kinase activity by modulating dRassf inhibition of hpo39, we found that double conditional knockout of Mst1/2, the mammalian homolog of hpo, with Nestin Cre did not elicit a hydrocephalus phenotype (unpublished data)." (PMID 26754915, 2016).
ischemic stroke (1 paper, 2018). A stroke disorder caused by obstruction of blood flow to the brain, due to thrombotic (local blood clot formation) or embolic (due to a blood clot or other material traveling from another site) event. "Furthermore, genetic deletion of MST1 provides neuroprotection against ischemic stroke and spinal cord injury by attenuating neuronal apoptosis and the inflammatory response." (PMID 30018671, 2018). "Genetic deletion of MST1 may reduce the inflammation and microglial activation after spinal cord injury and ischemic stroke." (PMID 30018671, 2018). "Mammalian sterile 20-like kinase 1 (MST1), the key component of the Hippo-YAP pathway, exhibits an important role in the pathophysiological process of various neurological disorders, including ischemic stroke and spinal cord injury." (PMID 30018671, 2018).
Left ventricular dilatation (1 paper, 2019). Enlargement of the chamber of the left heart ventricle. "Furthermore, cardiac specific Mst1 overexpression was accompanied by left ventricular dilatation and reduced wall thickness." (PMID 30837882, 2019).
liver cirrhosis (1 paper, 2024). "In this setting, CCl4 was administered for 12 weeks after the tail vein injection of Cre-expressing adenovirus (adeno-Cre) in Stk4(−/−)Stk3(F/−) (also known as Mst1(−/−)Mst2(F/−); F indicates a floxed allele) mice, and it resulted in the development of HCC tumors concomitantly with liver cirrhosis." (PMID 39062197, 2024).
liver steatosis (1 paper, 2022). "Excessive YAP signaling has been associated with liver steatosis and fibrosis in some preclinical models, but in a carbon tetrachloride injury model, YAP activation through MST1/2 inhibition decreased fibrosis." (PMID 35763355, 2022).